HIF1A (hypoxia inducible factor 1 subunit alpha)
Diseases named in the same sentence as HIF1A in open-access papers (continued):
Sharing a sentence is not in itself a finding about the gene and the disease.
Hypercholesterolemia (4 papers, 2020 to 2024). An increased concentration of cholesterol in the blood. "HIF1α, a key mediator under hypoxic conditions, was progressively upregulated during the various stages of hypercholesterolemia, which could reflect an adaptive mechanism to ischemic conditions within the atherosclerotic myocardium." (PMID 38610757, 2024). "We compared the effects of hypercholesterolemia on tissue culture, a mouse xenograft model, and a chemical carcinogenesis mouse model, and identified NOS1 as an unidentified direct target of HIF-1α that contributes to the oncogenic role of hypercholesterolemia in CRC." (PMID 38755702, 2024).
hypopharyngeal cancer (4 papers, 2017 to 2024). Carcinoma, predominantly squamous cell, arising from the epithelial cells of the hypopharynx. "No HIF-1α high expression cell lines were further constructed for retrospective study, and only the changes of HIF-1α expression in hypopharyngeal cancer cells treated with anlotinib were studied." (PMID 38330738, 2024). "Meanwhile, we also found that anlotinib could regulate the expression of HIF-1α in hypopharyngeal cancer cells." (PMID 38330738, 2024). "It suggested that anlotinib may inhibit the proliferation of hypopharyngeal cancer cells by regulating HIF-1α, which provides a new research direction for the mechanism of anlotinib." (PMID 38330738, 2024). "In the future, we will further investigate whether anlotinib can exert an inhibitory effect on hypopharyngeal cancer by directly targeting HIF-1α and regulating the expression of HIF-1α by changing local oxygen." (PMID 38330738, 2024). "In a cohort of oropharyngeal and hypopharyngeal cancer patients, a correlation between SUVmax, GLUT1, and HIF1a expression was found." (PMID 32984043, 2020). "HIF-1α and GTVp expression was a prognostic factor for PRFS in patients with hypopharyngeal cancer." (PMID 29069791, 2017). "In head‐and‐neck cell lines, TWIST1 was found to be an essential downstream target of HIF‐1α and that knockdown of TWIST1 led to a decreased number of metastatic nodules after either tail vein injection or orthotopic transplantation of hypopharyngeal cancer cell line with overexpression of HIF‐1α." (PMID 28085222, 2017).
hypoxia (4 papers, 2013 to 2025). A decrease in the amount of oxygen in the body. "HIF-1α polymorphisms have been extensively studied in order to determine the association they may have in the appearance or progression of hypoxia related diseases." (PMID 24260273, 2013). "We also verified the effect of the activation of ERK1/2 signaling on C/EBP β, c-Fos and HIF-1α regulation in hypoxia-induced retinopathy." (PMID 28374767, 2017).
intestinal cancer (4 papers, 2020 to 2024). "Recent findings underscore the role of CHSY1 in depleting CD8+ T cells through succinate metabolism activation and the PI3K/AKT/HIF1A pathway, facilitating liver metastasis in intestinal cancer." (PMID 38812506, 2024).
Kaposi's sarcoma (4 papers, 2016 to 2025). A malignant neoplasm characterized by a vascular proliferation which usually contains blunt endothelial cells. "Kaposi’s sarcoma associated herpesvirus (KSHV), a known cause of Kaposi’s sarcoma, has been found to stabilize hypoxia-inducible factor 1 alpha (HIF1α), a key regulator of cellular response to hypoxia." (PMID 39995663, 2025). "In Kaposi’s sarcoma, KSHV-encoded LANA protein maintains stem-like characteristics in endothelial progenitor cells through stabilization of HIF-1α and VEGF autocrine signaling." (PMID 41157571, 2025).
laryngeal tumor (4 papers, 2023 to 2025). "It was proven that high expression of HIF1A is related to poor outcomes in oropharynx and larynx tumors." (PMID 38928200, 2024). "High expression of HIF1α was noted in 18/33 laryngeal tumors." (PMID 36586079, 2023).
leiomyoma (4 papers, 2014 to 2026). A well-circumscribed benign smooth muscle neoplasm characterized by the presence of spindle cells with cigar-shaped nuclei, interlacing fascicles, and a whorled pattern. "The ULMs of patients with HLRCC are more vascularized and show more overexpression of HIF1α and vascular endothelial growth factor (VEGF) than do sporadic leiomyomas, and this should be considered by gynaecologists to prevent haemorrhagic complications at the time of surgery." (PMID 33167498, 2020).
lipid metabolic disorder (4 papers, 2021 to 2026). "Collectively, these findings suggest that DHQ ameliorates lipid metabolic disorders and inflammation in MASLD by modulating the HIF-1α/VEGF pathway, supporting its potential as a therapeutic candidate." (PMID 41684909, 2026). "In summary, Serpina3c inhibits the Hif1α-glycolysis pathway and reduces de novo lipogenesis (DNL) and LD secretion in adipocytes by binding to Nrf2, thereby improving HFD-induced lipid metabolism disorders and alleviating adipose tissue macrophage inflammation." (PMID 39693610, 2025).
lumbar disc degeneration (4 papers, 2013 to 2024). "A recent study suggests that HIF-1α polymorphism affects lumbar disc degeneration and confers the susceptibility to lumbar disc disease (LDD) in Chinese cohort." (PMID 25401740, 2014). "This study aimed to investigate whether or not hypoxia-inducible factor-1α (HIF-1α) gene variants are associated with the susceptibility and clinical characteristics of lumbar disc degeneration (LDD)." (PMID 23991178, 2013).
lymphoid leukemia (4 papers, 2013 to 2025). A malignant lymphocytic neoplasm of B-cell or T-cell lineage involving primarily the bone marrow and the peripheral blood. "Further, while HIF-1α plays an important role biologically and clinically in myeloid and lymphoid leukemias, we found that high AA strongly inhibited HIF-1α expression in leukemic cells." (PMID 23626851, 2013). "Another molecule that appears to play a key role in the antiproliferative action of AA is hypoxia-inducible factor 1α (HIF1α), already known to play an important biological role in both myeloid and lymphoid leukemias: HIF1α is actually activated in leukemic cells even in the absence of hypoxia." (PMID 36675247, 2023). "HIF-1α inhibition by echinomycin has been shown to inhibit cell proliferation and induce apoptosis in a number of malignant cell lines including myeloid and lymphoid leukemia cell lines." (PMID 28183349, 2017).
male infertility (4 papers, 2022 to 2025). The inability of the male to effect fertilization of an ovum after a specified period of unprotected intercourse. "This study shows that asthma can regulate the HIF-1 signaling pathway, promoting the expression of IL6, Stat3, and HIF-1α protein and mRNAs, so as to promote sperm apoptosis and ultimately causing male infertility." (PMID 35620222, 2022).
malnutrition (4 papers, 2014 to 2022). Inadequate nutrition resulting from poor diet, malabsorption, or abnormal nutrient distribution. "Consistent with this, HIF-1α was reduced in the PKM2 inhibition group under nutritional deficiency, and PKM2 inhibition can reduce the HIF-1a level induced by ATF4 silence under nutritional deficiency." (PMID 36324122, 2022). "Therefore cellular stress like hypoxia or malnutrition might activate HIF1α or β-catenin which induce ZEB1 and the global EMT program and finally lead to the induction of ER-stress." (PMID 24498091, 2014).
mastitis (4 papers, 2023 to 2025). Inflammation of breast tissue during lactation or postpartum due to an obstructed duct or infection. "Taurine can modulate HIF–1α, reduce inflammation and mammary tissue damage, and prevent mastitis dysfunction induced by Streptococcus uberis." (PMID 40005889, 2025). "The findings of the present study are in line with the previous study showing that the therapeutic effect of alpha-linolenic acid based intra-mammary nano-suspension on LPS induced mastitis in rat resulted in suppression of the HIF-1α." (PMID 35073659, 2024).
medullary thyroid cancer (4 papers, 2017 to 2023). "HIF1A expression correlated positively with Medullary thyroid carcinoma prognosis (MTC)." (PMID 36937508, 2023).
mesothelioma (4 papers, 2015 to 2026). A usually malignant and aggressive neoplasm of the mesothelium which is often associated with exposure to asbestos. "A decrease in nuclear HIF-1α signal was observed in mesothelioma cases with germline BAP1 mutations, particularly those with biallelic mutations, which revealed BAP1’s interaction with HIF-1α." (PMID 41602827, 2026).
metastatic prostate carcinoma (4 papers, 2013 to 2023). A carcinoma that arises from the prostate gland and has spread to other anatomic sites. "However, such variations in HIF-1α mRNA expression in T-allele carriers, are in accordance with the large variation of leukocyte HIF-1α expression in septic patients, as well as a worse outcome of T-allele carriers with metastatic prostate cancer." (PMID 27515179, 2016). "Regardless of the hypoxic condition of the tumor, therapeutic inhibition of HIF1α may be of use in the treatment of metastatic prostate cancer." (PMID 23342109, 2013). "Furthermore, patients with tumors that were positive for HIF1α were at a 10-fold higher risk of developing castrate resistance (p = 0.021) and 9.8-fold higher risk of progressing to metastatic prostate cancer (p = 0.017) than patients not expressing HIF1α." (PMID 23342109, 2013).
multiple sclerosis (4 papers, 2025 to 2026). A progressive autoimmune disorder affecting the central nervous system resulting in demyelination. "Notably, HIF-1α deficiency in myeloid cells reversed neurological symptoms and reduced IL-1β and IL-17 production in a mouse model of multiple sclerosis with Pg infection." (PMID 40494891, 2025).
myocarditis (4 papers, 2021 to 2024). Myocarditis is a condition that is characterized by inflammation of the heart muscle (myocardium). "HIF-1α has been reported to be positively correlated with myocarditis severity in patients with CCM." (PMID 38062533, 2023). "The aim of this study was to investigate the role of hypoxia-inducible transcription factor (HIF)-1α and its inhibitor topotecan in the pathogenesis of myocarditis." (PMID 34465337, 2021). "Existing study has shown that HIF-1α expression in cardiac leukocytes correlates with the severity of myocarditis in end‐stage Chagas disease patients." (PMID 34465337, 2021). "To conclude, these findings demonstrated that HIF-1α inhibition by topotecan ameliorates LPS-induced myocarditis in vitro, providing a new approach in the treatment of myocarditis." (PMID 34465337, 2021). "It has been reported that the expression of HIF-1α in cardiac leukocytes correlates with the severity of myocarditis in end-stage Chagas disease patients." (PMID 34465337, 2021). "In the present study, we aimed to explore the roles of HIF-1α and topotecan in the inflammation and apoptosis of cardiomyocytes induced by LPS, which is an in vitro cell model to simulate myocarditis followed by Gram-negative bacterial infection." (PMID 34465337, 2021). "However, the lack of study about the effects of HIF-1α and topotecan in myocarditis animal model is a limitation of the present research and therefore, a comprehensive analysis is required in the future." (PMID 34465337, 2021).
necrotizing enterocolitis (4 papers, 2022 to 2025). Necrotizing enterocolitis (NEC) is a devastating disease that affects mostly the intestine of premature infants. "In necrotizing enterocolitis (NEC), elevated fecal succinate levels were associated with disease severity, and succinate-mediated activation of the HIF-1α pathway was implicated in disease progression." (PMID 41000375, 2025). "The findings suggest that the HIF1A rs11549465T allele is an independent protective factor against necrotizing enterocolitis (NEC), but may increase the risk of diffuse white matter injury (DWMI) in newborns exposed to hypoxia at birth and long-term oxygen supplementation." (PMID 37239335, 2023). "Succinate plays an important role in the development of necrotizing enterocolitis severity, and the activation of the HIF-1a signaling pathway may lead to disease progression." (PMID 36519131, 2022).
oropharyngeal squamous cell carcinoma (4 papers, 2012 to 2024). "However, in a cohort of patients with oropharyngeal squamous cell carcinoma there was some evidence for HIF-1α expression in the tumour associating with clinical outcome." (PMID 33113858, 2020). "This study aimed at defining the metabolic program activated by HIF-1α in oropharyngeal squamous cell carcinomas (SCC) and assessing its clinical impact." (PMID 28099149, 2017). "In summary, through bioinformatics analysis and immunohistochemistry, we hypothesize the involvement of HIF-1a in regulating TDO2 gene expression and downstream glycolytic pathways in HPV-positive oropharyngeal squamous cell carcinoma." (PMID 38887298, 2024).
polycystic kidney disease (4 papers, 2017 to 2025). A usually autosomal dominant and less frequently autosomal recessive genetic disorder characterized by the presence of numerous cysts in the kidneys leading to end-stage renal failure. "The polycystic kidney has been shown to express HIF1α in tubular epithelial cysts, providing evidence that it experiences hypoxia." (PMID 33255651, 2020). "Taken together, the polycystic kidney experiences increased levels of tissue hypoxia, while the proposed HIF1α, ΤΜΕΜ16A, ion secretion axis, which is shown to exacerbate disease, may become a successful target for therapy." (PMID 33255651, 2020).
polycystic ovary syndrome (4 papers, 2021 to 2025). A disorder that manifests as multiple cysts on the ovaries. "Among these, two downregulated genes have previously been associated with premature ovarian insufficiency (POI): Gja1, which is essential for oocyte–cumulus communication and implicated in polycystic ovarian syndrome, and Hif1a, a regulator of follicular development via hypoxia pathways." (PMID 41278955, 2025). "Another study found that HIF-1α improved endometrial receptivity in patients with polycystic ovary syndrome." (PMID 33419445, 2021). "Inhibition of HIF-1a expression was found to have triggered atresia in large follicles of mice with polycystic ovary syndrome (PCOS) and, therefore, prevented ovulation." (PMID 34394393, 2021).
postmenopausal osteoporosis (4 papers, 2014 to 2025). Metabolic disorder associated with fractures of the femoral neck, vertebrae, and distal forearm. "Recently, we reported that hypoxia inducible factor 1 alpha (HIF1α) is required for osteoclast activation following estrogen-deficiency and for development of postmenopausal osteoporosis in animal models." (PMID 25375896, 2014). "In this study, we found that both ED71, which is used as therapeutic agents for postmenopausal osteoporosis therapy, inhibits HIF1α protein expression." (PMID 25375896, 2014). "Additionally, HIF-1α transcription was inhibited by zoledronic acid, a conventional drug for the treatment of postmenopausal osteoporosis, and was accompanied by a marked inhibition of the RAS/MAPK/ERK1/2 pathway." (PMID 25929338, 2015). "This study suggests that HIF1α could be a therapeutic target for postmenopausal osteoporosis." (PMID 25375896, 2014). "Thus, blocking HIF1α pharmacologically could represent an ideal treatment for postmenopausal osteoporosis, as it could target pathologically-activated osteoclasts without altering physiological osteoclastogenesis required for bone turnover." (PMID 25375896, 2014). "HIF-1α effectively binds to the HRE region in the Rankl promoter, leading to increased RANKL production and enhanced osteoclastogenesis in a model of postmenopausal osteoporosis." (PMID 35177582, 2022). "Since inhibition of osteoclast activity was seen in the patients treated with ED71 but not with 1,25(OH)2D3, this work confirms that HIF1α could be a target to treat postmenopausal osteoporosis patients." (PMID 25375896, 2014).
pregnancy disorder (4 papers, 2014 to 2020). A disorder that is related to pregnancy. "Our model has provided an example of how pregnancy disorders can be affected by a dysregulation of Hif1α induced by other genetic mutations." (PMID 32784053, 2020). "It has been asserted that exposure to TCDD via induced HIF-1α stabilization increases the risk of abnormal trophoblast differentiation and function and is the basis of many placenta-based pregnancy disorders, including pre-eclampsia and fetal growth restriction." (PMID 25272228, 2014). "Therefore, a dysregulation of Hif1α expression caused by any genetic defect or environmental influence in early pregnancy could be the root cause of pregnancy disorders." (PMID 32784053, 2020). "The HIF1a is the molecular link between hypoxia and pregnancy disorders as it induces antiangiogenic factor sFlt1 and vasoconstrictor Urotensin-II." (PMID 27626035, 2016). "An intriguing aspect to the present work is the suggestion that HIF-1α/VEGF may play an important role in the development of placental insufficiency-related pregnancy disorders, such as missed abortion." (PMID 29951709, 2018).
rectal adenocarcinoma (4 papers, 2009 to 2025). "In this study, we investigate one of the largest cohorts of patients to date with rectal adenocarcinoma across all stages for HIF-1α and HIF-2α expressions and have appraised associations between expression and a number of clinicopathological variables." (PMID 19436307, 2009).
schizophrenia (4 papers, 2019 to 2025). A major psychotic disorder characterized by abnormalities in the perception or expression of reality. "Interestingly, a recent combined analysis of gene expression and GWAS data in schizophrenia showed a strong signal for HIF1A in the dorso-lateral prefrontal cortex." (PMID 32477182, 2020).
Seizure (4 papers, 2019 to 2023). A seizure is an intermittent abnormality of nervous system physiology characterized by a transient occurrence of signs and/or symptoms due to abnormal excessive or synchronous neuronal activity in the brain. "Seizure commonly causes hypoxia in neurons, and hypoxia and HIF1α are well-known to cause increased oxidative stress and inflammation in the brain." (PMID 34021541, 2021).
Splenomegaly (4 papers, 2017 to 2026). Abnormal increased size of the spleen. "Because, L. donovani infection leads to splenomegaly and chronic inflammation, we next wanted to know if HIF-1α was involved at all in the immune response to the parasite during persistent infection." (PMID 29472618, 2018). "Despite the fact that HIF-1α is involved in promoting endothelial cell proliferation and Ly6Chi monocytes contribute to red pulp vasculature remodelling, this transcription factor doesn’t seem to be the major player in tissue neovascularization and splenomegaly in experimental VL." (PMID 28892492, 2017). "At this time point of infection, mice have not yet developed severe splenomegaly, the splenic architecture is still intact, and HIF-1α expression in myeloid cell is very low." (PMID 28892492, 2017). "Indeed, CD11c-HIF-1α conditional knockout and HIF-sufficient animals developed similar levels of splenomegaly and myeloid cells from both group of mice expressed similar levels of vascular endothelial growth factor (VGEF) mRNA." (PMID 28892492, 2017).